GPD1 (glycerol-3-phosphate dehydrogenase 1)
Description:
Has glycerol-3-phosphate dehydrogenase activity.
Synonyms: GPD-C; GPDH-C; HTGTI
Tractability: Small molecule: a structure with a bound ligand is known. PROTAC: its protein half-life has been measured.
Gene: Protein-coding gene on chromosome 12 (50,103,982 to 50,111,316, forward strand). Ensembl gene ENSG00000167588.
Subcellular location: Cytoplasm
Pathways (Reactome):
Metabolism: Synthesis of PA
Gene Ontology:
Molecular function: protein binding; glycerol-3-phosphate dehydrogenase (NAD+) activity; glycerol-3-phosphate dehydrogenase [NAD(P)+] activity; NAD binding; oxidoreductase activity, acting on the CH-OH group of donors, NAD or NADP as acceptor; protein homodimerization activity
Biological process: glycerol-3-phosphate metabolic process; carbohydrate metabolic process; glycerol-3-phosphate catabolic process
Cellular component: cytoplasm; extracellular exosome; cytosol
Genetic constraint (gnomAD): Loss-of-function variants: 13 observed, 23.2 expected, observed/expected ratio (o/e) 0.56, 90% interval 0.36 to 0.89. The upper end of that interval is the gene's LOEUF score, 0.89, which puts it in group 3 of 6, group 1 being the genes least tolerant of losing a copy. Missense variants: 359 observed, 390.23 expected, observed/expected ratio (o/e) 0.92, 90% interval 0.84 to 1. Synonymous variants: 151 observed, 155.28 expected, observed/expected ratio (o/e) 0.97, 90% interval 0.85 to 1.11.
Homologues: Orthologues: chimpanzee GPD1 (99% identical), macaque GPD1 (98% identical), guinea pig GPD1 (95% identical), mouse Gpd1 (94% identical), rat Gpd1 (92% identical), dog GPD1 (90% identical), pig GPD1 (89% identical), zebrafish gpd1a (78% identical), zebrafish gpd1b (77% identical), tropical clawed frog gpd1 (76% identical), Drosophila melanogaster Gpdh1 (65% identical), Caenorhabditis elegans gpdh-2 (62% identical), and 3 more. Paralogues in human: GPD1L (71% identical).
Diseases named in the same sentence as GPD1 in open-access papers:
GPD1 is named in the same sentence as 69 diseases in open-access papers, as found by Europe PMC text mining. Sharing a sentence is not in itself a finding about the gene and the disease. The quoted sentences say what the papers report.
hypertriglyceridemia (19 papers, 2018 to 2026). A laboratory test result indicating elevated triglyceride concentration in the blood. "In patients with transient infantile hypertriglyceridemia, investigation into novel homozygous variants in the GPD1 gene should be conducted using whole exome sequencing." (PMID 40216993, 2025). "Herein, we report 2 siblings with a novel homozygous variant of the GPD1 gene, characterized by elevated liver enzymes, hypertriglyceridemia, and hepatosteatosis." (PMID 40216993, 2025). "Nevertheless, the precise mechanism underlying hypertriglyceridemia in GPD1 deficiency remains elusive and necessitates additional clarification." (PMID 40216993, 2025). "We report 2 siblings with novel homozygous variants in the GPD1 gene with transient infantile hypertriglyceridemia." (PMID 40216993, 2025). "Subsequently, several clinical mutations in GPD1 have been reported with consistent phenotypes, such as hepatomegaly, steatosis, or hypertriglyceridemia, often in infants." (PMID 38689091, 2024). "Given that GPD1 mutation is associated with transient infantile hypertriglyceridemia, the disease association and intracellular localization seem different from those of GPD1L." (PMID 38689091, 2024). "Mutations in the glycerol-3-phosphate dehydrogenase 1 (GPD1) gene (located on chromosome 12q13.12) are the cause of transient infantile hypertriglyceridemia (hypertriglyceridemia, transient infantile, HTGTI)." (PMID 37510094, 2023). "Common clinical features of GPD1-associated patients are hepatic steatosis (100%, 19/19), hepatomegaly (100%, 18/18), hypertriglyceridemia (95%, 18/19), and hypohepatia (elevated liver transaminases) (95%, 18/19)." (PMID 34484308, 2021). "We summarized the clinical presentations of transient infantile hypertriglyceridemia and also expanded the spectrum of disease-causing mutations in GPD1." (PMID 34484308, 2021). "Herein we report a Chinese girl with a hitherto unreported homozygous variant of the GPD1 gene, who presented with elevated transaminases, massive hepatomegaly, hepatic steatosis and hypertriglyceridemia from the age of 4 months." (PMID 34484308, 2021). "Biallelic mutations in the GPD1 gene cause a rare autosomal recessive inherited disease known as transient infantile hypertriglyceridemia." (PMID 33763395, 2021). "To date, only 24 different GPD1 mutations have been reported in the literature worldwide with transient infantile hypertriglyceridemia or relevant conditions." (PMID 34484308, 2021). "In future clinical diagnosis, GPD1 deficiency should be considered if hypertriglyceridemia, elevated liver enzymes, hepatomegaly, hepatic steatosis and fibrosis are present in early infancy." (PMID 34484308, 2021). "Another study found that GPD1 mutations can lead to hypertriglyceridemia and a fatty liver in infants." (PMID 34098990, 2021). "Transient infantile hypertriglyceridemia is caused by an autosomal recessive variant in the glycerol-3-phosphate dehydrogenase 1 (GPD1) gene that causes defective lipid synthesis and a high rate of triglyceride secretion by the liver." (PMID 34146174, 2021). "Here, we describe a Han Chinese patient with a novel GPD1 homozygous mutation who presented with hepatomegaly, elevated transaminases, hypertriglyceridemia, and fatty liver in infancy." (PMID 29940878, 2018). "Studies have found that GPD1 gene mutation can lead to hypertriglyceridemia (HTG)." (PMID 40631874, 2025). "Furthermore, analysis of whole-exome sequencing data did not identify any CNV nor pathogenic variants in glycerol-3-phosphate dehydrogenase 1 (GPD1) to exclude possible Transient Infantile Hypertriglyceridemia." (PMID 35669187, 2022). "In summary, we report a Chinese HTGTI female patient with a noval mutation of GPD1 who presented with transient infantile hypertriglyceridemia, jaundice, hepatomegaly, elevated transaminases, and hepatic steatosis, providing references for the expansion of HTGTI's gene mutation spectrum." (PMID 33907148, 2021).
hypertriglyceridemia (continued). "Our patient has characteristics of GPD1 deficiency includes early-onset, elevated ALT and γ-GT levels, hypertriglyceridemia, fatty liver and mild failure to thrive." (PMID 34484308, 2021).
breast carcinoma (10 papers, 2017 to 2024). "Glycerol-3-phosphate dehydrogenase 1 (GPD1) is a tumor suppressor within breast cancer and reduced expression of GDP1 is associated with poor overall survival." (PMID 37621676, 2023). "Particularly for breast cancer, a proteomics-based study revealed the lowest expression of GPD1 protein in triple-negative breast cancer (TNBC), suggesting a possible relationship between GPD1 and hormone receptors in breast cancer." (PMID 38689091, 2024). "As miR-370 is known to be upregulated in breast cancer cells and related to tumor progression, this study revealed an upstream regulator of GPD1 in breast cancer." (PMID 38689091, 2024). "In this study, we explored the lipid regulatory pathway in breast cancer GPD1 overexpression cells and its underpinning mechanisms." (PMID 37483742, 2023). "We further determined the effect of GPD1 on the ability of migration and invasion in breast cancer cells." (PMID 37483742, 2023). "In summary, our study confirmed that GPD1 inhibits the ability of proliferation, migration, and invasion in breast cancer cells via activating the PI3K/AKT-mediated lipid signaling pathway." (PMID 37483742, 2023). "The mRNA and protein expression levels of GPD1 in breast cancer cells were examined by RT-qPCR and western blotting." (PMID 37483742, 2023). "We confirmed that GPD1 inhibited the ability of proliferation, migration, and invasion in GPD1 overexpression breast cancer cells by CCK-8, wound healing, and Transwell assays, respectively." (PMID 37483742, 2023). "Meanwhile, we detected that the relationship between GPD1 level and survival rate presents a positive correlation in breast cancer patients from the Cancer Genome Atlas (TCGA) database." (PMID 37483742, 2023). "The inhibitory effect of GPD1 on breast cancer cells was also weakened after treatment with LY294002, a PI3K/AKT pathway inhibitor." (PMID 37483742, 2023). "Meanwhile, the survival of breast cancer was a significant difference between the GPD1 expression level and menopause status (p < 0.01)." (PMID 37483742, 2023). "In this study, we found that GPD1 overexpression inhibited proliferation, migration, and invasion in breast cancer cells by activating PI3K/AKT signaling pathway and lipogenesis." (PMID 37483742, 2023). "Meanwhile, the expression level of GPD1 has a positive correlation with lipid metabolites and the survival rate of breast cancer patients, respectively." (PMID 37483742, 2023). "The ability of cell proliferation was also partly recovered in breast cancer cells compared with the GPD1 overexpression group using the CCK-8 assay kit." (PMID 37483742, 2023). "The elevated p-GSK3β expression level of the GPD1 overexpression group indicated that GPD1 inhibited glycogen synthesis in breast cancer cells." (PMID 37483742, 2023). "The overall survival of GPD1 high expression level in breast cancer patients partially exceeded the populations of GPD1 low or medium expression level, although the results were not significant." (PMID 37483742, 2023). "Relevant studies reported that GPD1 presented lower expression levels in the mRNA plane of breast cancer cells not only, but also in the protein plane of breast cancer tissues." (PMID 37483742, 2023). "Based on individual cancer stages, the GPD1 expression levels were also reduced to 3.74, 1.21, 1.67, and 0.85 in breast cancer compared with that in the normal group (p < 0.001)." (PMID 37483742, 2023). "In the TCGA database, GPD1 mRNA was shown to be at low levels in multiple tumor types, including breast cancer, lung cancer, and prostate cancer." (PMID 35836291, 2022). "The expression level of GPD1 is significantly downregulated in human breast cancer patients, and overexpression of GPD1 markedly suppresses cell proliferation, migration, and invasion of breast cancer cells." (PMID 35692369, 2022). "GPD1 has been identified as a tumor suppressor in breast cancer and exerts antitumor effects in lung and prostate cancers." (PMID 35836291, 2022).
breast carcinoma (continued). "Studies suggested that GPD1 was closely related to prognosis of gastrointestinal cancer, breast cancer, and glioblastoma." (PMID 33937273, 2021). "Our results indicate that breast cancer patients have significantly lower expression levels of GPD1 compared with normal controls, which was further verified in 63 paired human breast cancer tissues (54 out of 63) compared with the adjacent normal tissues." (PMID 29254166, 2017). "In conclusion, the current study identified correlations between GPD1 expression in breast cancer and highlights the prognostic value of GPD1 mRNA levels in breast cancer." (PMID 29254166, 2017). "We also determined the mRNA expression levels of GPD1 in a normal breast cell line and five human breast cancer cell lines." (PMID 29254166, 2017). "MTT assays were further performed, and as expected, transfection with the GPD1 expression plasmid decreased the proliferation of MCF-7 breast cancer cells compared with control cells which transfected with empty vector." (PMID 29254166, 2017). "We also found that miR-370 was significantly upregulated in the majority of paired human breast cancer tissues compared with the adjacent normal tissues (p < 0.001), and the miR-370 levels were inversely correlated with GPD1 levels (r = −0.716, p < 0.001)." (PMID 29254166, 2017). "Using the criterion value of 0.60, the sensitivity and specificity values were 0.81 and 0.86, respectively, to identify a patient with breast cancer, indicating that GPD1 serves as an excellent human breast cancer marker." (PMID 29254166, 2017). "We also analysed the expression of GPD1 in human breast cancer patients with different ages (N = 3,552), Scarff-Bloom-Richardson grading (SBR, N = 3,470) and Nottingham prognostic indexes (N = 1,762)." (PMID 29254166, 2017). "Taken together, the results suggest that miR-370 directly suppress GPD1 expression in human breast cancer." (PMID 29254166, 2017). "The results showed that GPD1 was significantly downregulated in the majority of the paired human breast cancer tissues (54 out of 63) compared with the adjacent normal tissues (p < 0.001)." (PMID 29254166, 2017). "In the present study, we found the mRNA expression level of glycerol-3-phosphate dehydrogenase (GPD1) was significantly downregulated in human breast cancer patients." (PMID 29254166, 2017). "We further evaluated migration and invasion of human breast cancer cells by examining the effects of exogenous GPD1." (PMID 29254166, 2017). "By using the Bc-GenExMiner v4.0 database, we analysed the GPD1 expression in human breast cancer patients with several splitting criteria, including receptor status and molecular subtype." (PMID 29254166, 2017). "We also found that GPD1 protein levels were significantly decreased in three pairs of human breast cancer tissues compared with normal tissues." (PMID 29254166, 2017). "To consolidate our findings at the mRNA level, we performed IHC to investigate the protein level of GPD1 in all of the 63 paired breast cancer tissues which were used above." (PMID 29254166, 2017). "We also demonstrated that GPD1 was a direct target of miR-370, which was significantly upregulated in human breast cancer." (PMID 29254166, 2017). "Western blot analysis demonstrated that the protein level of GPD1 was also downregulated in human breast cancer cell lines when compared with a normal breast cell line." (PMID 29254166, 2017). "In this study, we first identified the expression level of GPD1 using TCGA and Oncomine databases, and further evaluated the prognostic value of GPD1 expression in human breast cancer through meta-analysis of public microarray profiles." (PMID 29254166, 2017). "To further investigate the relationship between GPD1 and miR-370, we analysed the expression of miR-370 in breast cell lines and 63 paired breast cancer tissues." (PMID 29254166, 2017).
breast carcinoma (continued). "GPD1 was significantly downregulated in human breast cancer cell lines (MCF-7, MDA-MB-231, MDA-MB-468, SKBR-3 and SUM159) when compared with a normal breast cell line (Hs-578Bst)." (PMID 29254166, 2017). "Moreover, the expression level of GPD1 existed an obvious change in different races of breast cancer patients." (PMID 37483742, 2023). "Existing studies have shown that GPD1 may inhibit the proliferation, migration, and invasion of breast cancer cells." (PMID 37024893, 2023). "This study aims to explore the function and clinical relevance of GPD1 in breast cancer." (PMID 37483742, 2023). "Although relevant studies found that GPD1 has lower expression at both the transcriptional level and protein level in breast cancer cells, the functions of GPD1 remain largely unknown, particularly in lipid metabolism and signaling pathways." (PMID 37483742, 2023). "Therefore, GPD1 can be a prognostic biomarker and target in developing therapeutic strategies for breast cancer patients." (PMID 37483742, 2023). "Accumulating evidence indicates that GPD1 also plays a suppressive role in various cancer, including lung cancer, renal clear cell carcinoma, glioblastoma, bladder cancer, and breast cancer." (PMID 37483742, 2023). "GPD1 expression has been found to be low in prostate, lung, and breast cancers, and GPD1 was shown to have antitumor effects, which is consistent with our findings and predicts that GPD1 may be a potential therapeutic target in bladder cancer." (PMID 35836291, 2022). "We first queried the expression pattern of GPD1 in human breast cancer." (PMID 29254166, 2017). "Furthermore, a consistent result for GPD1 expression in breast cancer was found in the Oncomine database." (PMID 29254166, 2017). "We found that the GPD1 expression level has significant prognostic value for breast cancer patients with ER-positive tumours (for NM, ER+, AE: p = 0.0027, HR = 0.91, 95% CI = 0.85–0.97, NP = 3,917, NE = 1,248 and for NM, ERM, AE: p = 0.0005, HR = 0.91, 95% CI = 0.86–0.96, NP = 5,488, NE = 1,854)." (PMID 29254166, 2017). "However, little is known about the role of GPD1 in human cancers, particularly in human breast cancer." (PMID 29254166, 2017). "In addition, we confirmed that GPD1 can inhibit breast cancer cell proliferation, migration, and invasion." (PMID 29254166, 2017). "Moreover, the composite biomarker models integrating GPD1 and lipid metabolites could robustly improve the prognostic accuracy or survival in breast cancer patients." (PMID 37483742, 2023). "Therefore, the study suggested that AC245452.1 may be involved in the occurrence of luminal A breast cancer by regulating the GPD1 and PLIN1." (PMID 35692369, 2022). "The CCK-8 assay revealed that the overexpression of GPD1 inhibited cell proliferation in MCF-7 and MDA-MB-231 breast cancer cells." (PMID 37483742, 2023). "However, the GPD1-induced signaling pathway in breast cancer carcinogenesis was unknown." (PMID 37483742, 2023). "According to the lower expression level of GPD1, we established the GPD1 overexpression breast cancer cell lines (MCF7-GPD1 and 231-GPD1) via lentiviral vector and plasmid vector transduction, respectively." (PMID 37483742, 2023). "However, the mechanisms of GPD1 anti-tumor remain unclear in breast cancer." (PMID 37483742, 2023). "Up-regulated expression of COL10A1, MMP11, CST1, GJB2, MMP1, MMP13, and CEACAM6; down-regulated expression of ADH1B, CIDEC, THRSP, GPD1, TIMP4, FABP4, and SCARA5 genes was common in breast cancers of the two populations." (PMID 31292488, 2019). "We further showed that exogenous expression of GPD1 in human MCF-7 and MDA-MB-231 breast cancer cells significantly inhibited cell proliferation, migration, and invasion." (PMID 29254166, 2017). "Notably, we further found that exogenous expression of GPD1 in human MCF-7 and MDA-MB-231 breast cancer cell lines significantly inhibited cell proliferation, migration and invasion." (PMID 29254166, 2017).
breast carcinoma (continued). "Alternatively, there could be another correlation between GPD1 and PLIN1 in the progression of breast cancer." (PMID 29254166, 2017). "In addition, in the breast cancer subtypes according to the prediction analysis of microarray 50 (PAM50), luminal A subtype showed the highest GPD1 mRNA level compared with luminal B, HER2-enriched and basal-like subtypes." (PMID 29254166, 2017).
brain tumor (5 papers, 2022 to 2024). "For this purpose, brain tumor cells upregulate GPD1 to switch the metabolic flow to lipid metabolism by making use of the glycolysis metabolite DHAP, which was also reported to be the only sensor metabolite of the mTOR pathway in glycolysis." (PMID 38273014, 2024). "This is consistent with the finding in brain tumor stem cells that GPD1 is essential for the maintenance of cancer stemness and the most significantly changed lipid pathway is glycerophospholipid metabolism." (PMID 35563509, 2022). "However, specific expression of GPD1 was observed in brain tumor stem cells and was involved in tumor initiation." (PMID 35836291, 2022). "However, GPD1 acts as a brain tumor stem cell marker to promote the progression of glioblastoma." (PMID 35836291, 2022). "The expression of glycerol-3-phosphate dehydrogenase 1 (GPD1) and the B-cell lymphoma 2 gene (BCL-2) is frequently observed in leukemia and brain tumor cells that are in a dormant state." (PMID 38994941, 2024). "This is consistent with our previous finding that GPD1 (glycerol-3-phosphate dehydrogenase 1), which converts DHAP into G3P, is specifically expressed in brain tumor stem cells but not in neural stem cells." (PMID 38273014, 2024).